MTCL3 (MTCL family member 3)
Synonyms: C6orf174; SOGA3; dJ403A15.3
Tractability: Antibody: UniProt predicts a signal peptide or a membrane-spanning region. PROTAC: ubiquitination databases record sites on it.
Gene: Protein-coding gene on chromosome 6 (127,472,806 to 127,519,335, reverse strand). Ensembl gene ENSG00000214338.
Subcellular location: Membrane
Subcellular location (Human Protein Atlas): Cytosol; Nucleoplasm
Gene Ontology:
Biological process: regulation of autophagy
Cellular component: membrane
Genetic constraint (gnomAD): Loss-of-function variants: 45 observed, 61.83 expected, observed/expected ratio (o/e) 0.73, 90% interval 0.57 to 0.93. The upper end of that interval is the gene's LOEUF score, 0.93, which puts it in group 3 of 6, group 1 being the genes least tolerant of losing a copy. Missense variants: 1,116 observed, 1,180.7 expected, observed/expected ratio (o/e) 0.95, 90% interval 0.9 to 0.99. Synonymous variants: 570 observed, 514.83 expected, observed/expected ratio (o/e) 1.11, 90% interval 1.03 to 1.19.
Homologues: Orthologues: chimpanzee MTCL3 (99% identical), macaque SOGA3 (98% identical), pig MTCL3 (95% identical), mouse Mtcl3 (91% identical), dog MTCL3 (88% identical), rat Mtcl3 (88% identical), zebrafish mtcl3a (58% identical), zebrafish mtcl3b (54% identical), tropical clawed frog MTCL3 (36% identical). Paralogues in human: MTCL1 (43% identical), MTCL2 (32% identical).
Diseases named in the same sentence as MTCL3 in open-access papers:
MTCL3 is named in the same sentence as 3 diseases in open-access papers, as found by Europe PMC text mining. Sharing a sentence is not in itself a finding about the gene and the disease.
MTCL3 shares sentences with these, for which no sentence is quoted: diabetes (1 paper); kidney damage (1); tumour (1).